RUNX3 (RUNX family transcription factor 3)
Diseases named in the same sentence as RUNX3 in open-access papers (continued):
Sharing a sentence is not in itself a finding about the gene and the disease.
hepatocellular carcinoma (40 papers, 2007 to 2026). A malignant tumor that arises from hepatocytes. "RUNX3 is frequently down-regulated in gastric, breast, colorectal, renal, and hepatocellular cancers through point mutations, promoter hypermethylation, and cytoplasmic translocation." (PMID 40430278, 2025). "Immunohistochemistry results revealed a decrease in hepcidin expression in the Runx3 KD hepatocellular carcinoma cells." (PMID 34611951, 2021). "Down‐regulation of these genes was also observed in Runx3 knock‐down (KD) in both HepaRG cells, which are functional human hepatocytes, and HepG2 cells, which are human hepatocellular carcinoma cells." (PMID 34611951, 2021). "A tumor suppressive role of RUNX3 in vitro is described for Wilm’s tumor, prostate cancer, hepatocellular carcinoma, lung cancer and glioma." (PMID 33482905, 2021). "Consistently, RUNX3 restoration downregulates cancer stem cell (CSC) signaling in hepatocellular carcinoma through Jagged1-Notch signaling." (PMID 34336665, 2021). "The effect of Runx3 knock‐down (KD) was also investigated using siRNA‐mediated KD in functional human hepatocytes and human hepatocellular carcinoma cells." (PMID 34611951, 2021). "The Runx3 KD effect also confirmed using HepG2 cells, which are human hepatocellular carcinoma cells." (PMID 34611951, 2021). "For instance, RUNX3 was previously shown to inhibit hepatocellular carcinoma growth in vitro and in vivo in combination with Adriamycin33." (PMID 32922961, 2020). "MiR-106b-5p plays a carcinogenic role in hepatocellular carcinoma through regulating the target gene RUNX3." (PMID 33063118, 2020). "MiR-130a also increases drug resistance by regulating RUNX3 and Wnt signaling in cisplatin-treated hepatocellular carcinoma cells." (PMID 29225578, 2017). "miR-130a is upregulated in cisplatin-treated hepatocellular carcinoma cells to increase drug resistance, but downregulated in diabetic endothelial progenitor cells by targeting RUNX3." (PMID 26375442, 2015). "This inconsistence also occurred to miR-130a, which was shown to not only inhibit tumor suppressor RUNX3 in hepatocellular carcinoma but also suppress proto-oncogene MET in lung cancer." (PMID 23302469, 2013). "Hypermethylation of the RUNX3 promoter region has been correlated with various metastatic malignancies, such as breast, non-small cell lung, gastric, pancreatic, colorectal, or hepatocellular carcinomas." (PMID 21203558, 2010). "For instance, in hepatocellular carcinoma cells, up-regulation of circLARP4 could induce cellular senescence and cell cycle arrest through modulation of miR-761/RUNX3 axis." (PMID 35865636, 2022). "In line with this hypothesis, miR-130a upregulation was also shown to activate Wnt signalling in hepatocellular carcinoma cells by targeting RUNX3 expression." (PMID 32272867, 2020). "In the present study, hepatocellular carcinoma (HCC) microarray analysis showed that RUNX3 expression was significantly lower in HCC tissues compared with that in adjacent non-tumor tissues, and was negatively associated with metastasis and TNM stage." (PMID 28977878, 2017). "Thus, Runx2 and Runx3 might act as tumour suppressors in malignant melanoma, and Runx3 in breast, gastric, colon, and hepatocellular carcinomas, as well as non-small cell lung cancer." (PMID 17876328, 2007). "MiR-20a-5p overexpression contributed to hepatocellular carcinoma (HCC) cell proliferation and migration through reducing the translation of RUNX3." (PMID 34587164, 2021). "Ectopic expression of RUNX3 reportedly promoted E-cadherin expression, but had a negative effect on vimentin in hepatocellular carcinoma cells." (PMID 29254144, 2017). "According to recent reports, ectopic expression of RUNX3 promoted E-cadherin expression, but had a negative effect on Vimentin in hepatocellular carcinoma cells." (PMID 28977878, 2017).
lung carcinoma (40 papers, 2009 to 2025). "It was found that lung cancers with a TGFβ signature were more likely to experience genomic instability and mutational accumulation when they had lower expression levels of RUNX3." (PMID 37190015, 2023). "If Runx3 inactivation is essential for the maintenance of K-Ras-activated lung cancer, the survival of the model mice for activation via K-Ras alone should be directly related to the number of functional Runx3 alleles." (PMID 37887282, 2023). "Studies have shown that methylation of RUNX3 is a risk factor for the development of lung cancer and subsequent tumor progression." (PMID 29651226, 2018). "Both PDCD4 and RUNX3 are tumor suppressor genes, and their co-downregulation may be one of the causes of lung cancer." (PMID 33691643, 2021). "Several studies assessed the role of RUNX3 in malignancies such as gastric, colon, and lung cancers." (PMID 40650112, 2025). "To identify genes regulated by Runx3 in the K-Ras-activated lung cancer cells, we performed mRNA sequencing (RNA-seq) in KPR- cells and KPRrestored cells." (PMID 37887282, 2023). "It would be exciting indeed if Runx3 restoration eliminates K-Ras-activated lung cancer in an animal model." (PMID 36899846, 2023). "Arf expression in K-Ras-activated lung cancer was stopped upon Runx3 inactivation and recovered with Runx3 restoration." (PMID 37887282, 2023). "This study provides in vivo evidence supporting RUNX3 as a therapeutic tool for the treatment of K-RAS-activated lung cancers with a durable response." (PMID 37887282, 2023). "In this study, conditional restoration of Runx3 in an established K-Ras-activated mouse lung cancer model regressed both ADs and ADCs and suppressed cancer recurrence, markedly increasing mouse survival." (PMID 37887282, 2023). "RUNX3 restoration has been shown to eliminate K-RAS-activated tumors in a human lung cancer cell line." (PMID 36899846, 2023). "This mouse model was used to demonstrate that Runx3 restoration effectively regresses established lung cancers and inhibits recurrence." (PMID 37887282, 2023). "In this study, Runx3 restoration in a mouse lung cancer model regressed K-Ras-activated ADs as well as ADCs, suppressed secondary oncogene activation, and markedly extended the survival of mice (by approximately 15 weeks)." (PMID 37887282, 2023). "Further, an increase in RUNX3 level enhances the sensitivity to radiotherapy in lung cancer patients." (PMID 36479199, 2022). "Inactivation of RUNX3 was a crucial early event in the occurrence and development of lung malignancy, and upregulation of RUNX3 inhibited lung cancer cell growth." (PMID 25948105, 2015). "Runx3, a novel tumor suppressor gene, was found to be downregulated in gastric, colon and lung cancer." (PMID 24748977, 2014).
lung carcinoma (continued). "In the present study, exogenous Run3 was transiently expressed in AGS (human gastric adenocarcinoma), with undetectable Runx3 protein and in A549 (human lung carcinoma) with low levels of endogenous Runx3 protein." (PMID 24250365, 2011). "Second, based on the IHS data we have collected, the overall expression intensity of RUNX3 in lung cancer tissues is relatively weak, which may be related to the characteristics of the cancer itself." (PMID 40916017, 2025). "Alterations in epigenetics have been identified as crucial prognostic elements and potential therapeutic targets, with studies indicating that methylation patterns of specific genes, such as RASSF1A and RUNX3, are correlated with the prognosis and recurrence of lung cancer." (PMID 39440184, 2024). "This study identified Runx3 as such a tumor suppressor that could effectively regress established K-Ras-activated mouse lung cancer and inhibit cancer recurrence." (PMID 37887282, 2023). "RUNX3, which plays pivotal roles in lineage determination and functions as a tumor suppressor, is frequently inactivated in various types of human cancers, including stomach and lung cancers." (PMID 36899846, 2023). "In lung cancer cell lines, RUNX3 increases the expression of p21 and inhibits cell proliferation." (PMID 38093179, 2023). "MiR-301a can also directly bind with Runx3 to promote the malignant progression of lung cancer." (PMID 34931135, 2021). "Based on analysis of the transcription factor binding site and searching of reference 23, RUNX3 was hypothesized to activate the expression of CLDN1 in lung cancer." (PMID 32754286, 2020). "Meanwhile, the level of RUNX3 was positively correlated with that of CLDN1 in lung cancer cells also implied that RUNX3 might involve in the regulation of CLDN1 expression." (PMID 32754286, 2020). "Indeed, loss of RUNX3 is an early event in lung adenocarcinoma 67, suggesting the RUNX3-CLDN1 axis plays an essential role in repressing lung cancer progression." (PMID 32754286, 2020). "RUNX3 is a potent tumor suppressor in gastric cancer 66 and we demonstrated that lung cancer patients harboring the RUNX3-CLDN1 axis have better overall survival, suggesting RUNX3 may be a tumor suppressor in lung cancer." (PMID 32754286, 2020). "Runx3 knockdown can induce the downregulation of CXCL11 in lung cancer cells." (PMID 31708740, 2019). "In addition to lung cancer, there are more reports suggesting that RUNX3 can inhibit tumor development by affecting the growth, metastasis, and infiltration of renal cancer cells." (PMID 29651226, 2018). "RUNX3 promoter methylation was shown to have a frequency of 43.9% in blood samples of lung cancer." (PMID 29100425, 2017). "Therefore, identification of RUNX3 as a potential specific target for early-stage lung cancer eradication provides an important theoretical basis for the development of safer and more effective anti-cancer drugs." (PMID 25961920, 2016). "The activation and cross-talk of AMPKα and MEK/ERK1/2 signaling pathways, and reciprocal interplay of RUNX3 and FOXO3a expression contribute to the overall responses of baicalein, which unveils a novel molecular mechanism by which baicalein controls human lung cancer cell growth." (PMID 25948105, 2015). "Moreover, it has been reported that reduced expression of RUNX3 was observed in various cancers including bladder, liver, colon and lung cancers." (PMID 19521519, 2009).
lung carcinoma (continued). "In addition, Runx3 inactivation is an earlier event than K-Ras activation in a carcinogen-induced mouse lung cancer model that recapitulates the features of K-RAS-driven human lung cancers." (PMID 37887282, 2023). "However, RUNX3 has been reported to be methylated in lung cancer." (PMID 29796116, 2018). "However, the association between the effect of CpG-ODN on lung cancer cells and Runx3 expression has not been determined." (PMID 24748977, 2014). "In addition to its alteration in expression level, RUNX3 protein mislocalization from nucleus to cytoplasm was commonly reckoned as another risk factor leading to worse prognosis in cancer of stomach, colorectum, and breast, while not in lung cancer." (PMID 35368900, 2022). "RUNX3 forms a ternary complex with β-catenin/TCF to inhibit Wnt/β-catenin signaling in glioma and gastric, intestinal, and lung cancers 50-52." (PMID 32194819, 2020). "In addition, RUNX3 has been shown to destabilize the oncogenic protein MYC, thereby exerting a suppressive effect on gastrointestinal and lung cancers." (PMID 38430423, 2024). "RUNX3 is inactivated in most K-RAS-activated mouse and human lung cancers." (PMID 37887282, 2023). "In this study, Runx3-restored mouse lung cancer did not recur until 10 weeks after regression (14 weeks after Runx3 restoration)." (PMID 37887282, 2023). "However, most of the Tomato-positive lung cancer cells of KRL/F-TAM(+)-1w mice were TUNEL-positive, indicating that the Runx3-restored cells underwent apoptosis." (PMID 37887282, 2023). "We found that silencing of FOXO3a but not RUNX3 by siRNA approaches significantly reversed the baicalein-inhibited lung cancer cell growth." (PMID 25948105, 2015). "However, when lung cancer cells lacked RUNX3 proteins, TGFβ induced much higher levels of oxidative damage, which gets converted into DNA DSBs upon collision with replication forks." (PMID 37190015, 2023). "Therefore, under physiological conditions, in which oncogenic mutations are very rare, K-Ras activation alone is not sufficient, whereas its combination with Runx3 inactivation is sufficient, for lung cancer development." (PMID 36899846, 2023). "Although K-RAS-induced lung cancer development can proceed via multiple pathways, the high frequency of RUNX3 inactivation in K-RAS-induced mouse and human lung ADCs suggests that a major pathway involves R-point disruption by RUNX3 inactivation prior to K-RAS activation." (PMID 36899846, 2023). "We speculate that the reason for this phenomenon is the lack of expression of RUNX3 protein in lung cancer tissue, which weakens the anticancer effect and instead promotes the accumulation of a large number of noncancer cells, manifesting as nonfunctional enrichment or ineffective enrichment." (PMID 40916017, 2025). "The results of immunostaining showed that Arf was not expressed in KPRL/F-TAM(-) lung cancers, whereas it was expressed in KPRL/F-TAM(+) lung cancers in which Runx3 was restored." (PMID 37887282, 2023).
melanoma (28 papers, 2007 to 2024). A malignant, usually aggressive tumor composed of atypical, neoplastic melanocytes. "In this study, we used a metastatic cell model of mouse melanoma to further investigate the role of Runx3 in metastasis and to uncover the underlying transcriptional profile." (PMID 33672337, 2021). "Using a murine model for adoptive T cell therapy in melanoma, they demonstrated that transfer of Runx3-deficient CD8+ T cells (recirculating phenotype) resulted in increased mortality due to their inability to accumulate in tumors." (PMID 33019493, 2020). "Runx3 can be regarded as a tumor suppressor transcription factor which delays melanoma growth, mortality and enhanced tumor specific CD8+ T cell abundance." (PMID 38082437, 2023). "Previous studies have shown that RUNX3 can independently predict the prognosis of patients with melanoma, and that patients with positive RUNX3 expression have a better 5-year survival rate." (PMID 35116193, 2022). "Previous studies showed a significant decrease in RUNX3 expression in melanoma cell lines compared with melanocytes." (PMID 34639015, 2021). "We performed microarray analysis for the identification of differentially expressed genes (DEGs) regulated by Runx3 re-expression in B16-F10 (high-metastatic) melanoma cells." (PMID 33672337, 2021). "We previously demonstrated that Runx3 re-expression in B16-F10 melanoma cells changed their shape and attenuated their migration." (PMID 33672337, 2021). "Runx3 has also been shown to be a key driver in lymphocyte accumulation and differentiation in melanoma, potentially pointing to a future treatment target." (PMID 34445713, 2021). "In melanoma tissue, the expression of RUNX3 was decreased during cancer progression and was correlated with stage and five-year survival." (PMID 34639015, 2021). "In vivo, treatment of mice bearing a RUNX3-downregulated melanoma cell line with the demethylating agent resveratrol showed significantly reduced tumor growth (size and weight) in combination with increased RUNX3 expression." (PMID 34639015, 2021). "RUNX3 was strongly methylated in a metastatic melanoma cell line, and its expression was significantly elevated after 5-Aza-CdR (demethylating agent)." (PMID 34639015, 2021). "This is evident in preclinical murine melanoma models, where Runx3-shRNAmir knockdown resulted in diminished TRM cell accumulation within tumors, uncontrolled tumor growth, and low survival." (PMID 33019493, 2020). "To evaluate the function of miR-301a and Runx3 in regulating tumor metastasis, we intravenously injected the melanoma cell line (B16) and Lewis lung carcinoma (LLC1) cells into WT and miR-301a−/− mice." (PMID 31122259, 2019). "Runx3 is a major tumor suppressor gene and is frequently lost in various types of cancer (lung, gastric, colorectal, breast, bladder and melanoma), due to hemizygous deletions or epigenetic alterations." (PMID 23846726, 2013). "Specifically, FLRT2 was downregulated while MAD1L1, PHLDA2, PLAT, CC2D1B, CDKN2A and RUNX3 were upregulated in both melanoma and in Group 2 and Group 3 SFs." (PMID 23371019, 2013). "On the other hand, TSP-1 gene expression drastically increased at both the transcriptional and translational levels in response to Runx3 expression in B16-F10 melanoma cells." (PMID 23846726, 2013). "In particular, two of the RUNX3 probes (RUNX3_P247_F and RUNX3_P393_R) exhibited 100% sensitivity and 100% specificity in identifying melanomas." (PMID 21375697, 2011). "Loss of Runx3 expression has also frequently been found in melanoma cells as compared to melanocytes, and there is a good negative correlation between Runx3 expression and melanoma malignancy." (PMID 33672337, 2021). "Like PTEN, Runx3 may also function as a cell shape regulator when it suppresses melanoma cell migration and invasion in vitro." (PMID 33672337, 2021).